CDK1 (cyclin dependent kinase 1)
Diseases named in the same sentence as CDK1 in open-access papers (continued):
Sharing a sentence is not in itself a finding about the gene and the disease.
non-small cell lung carcinoma (29 papers, 2013 to 2026). A group of at least three distinct histological types of lung cancer, including non-small cell squamous cell carcinoma, adenocarcinoma, and large cell carcinoma. "Studies had shown that CDK1 expression was associated with prognosis in advanced non-small cell lung cancer, and low expression of CDK1 had a better prognosis." (PMID 31844590, 2019). "Among them, DLGAP5 could physically interact with PBK, TOP2A, and CDK1, and all mitosis-associated proteins correlated with poor prognosis for non-small cell lung cancer patients." (PMID 32426332, 2020). "Interestingly, Zhang and colleagues found that although Cdk1 was highly expressed in non-small cell lung cancer tissues, its loss from the cytoplasm predicted poor survival and conferred resistance to chemotherapy both in vivo and in vitro." (PMID 25511643, 2014). "Interestingly, Zhang and colleagues found that Cdk1 was highly expressed in non-small cell lung cancer tumor tissues, but its loss from the cytoplasm could predict poor prognosis." (PMID 25511643, 2014). "NCAPG-driven CDK1 facilitates the malignant progression of non-small cell lung cancer through ERK signaling activation." (PMID 40746552, 2025). "This study showed that bortezomib had a similar effect on CDK1 and cyclin B1 in non-small cell lung carcinoma cell lines." (PMID 37834095, 2023). "It identifies CDK1 as a potential biomarker and therapeutic target in the progression of non-small cell lung cancer." (PMID 35330393, 2022). "In contrast, Cucurbitacin-D-induced upregulation of CDK1 mRNA level has been shown to arrest the proliferation of non-small cell lung cancer." (PMID 35330393, 2022). "Most of the hub genes in the network like GAPDH, IL6, CDK1, PTEN, etc. are either associated with non-small cell lung cancer itself or other forms of cancers." (PMID 35330393, 2022). "For instance, the CDK1 inhibitor, purvalanol A, enhances the taxol-induced apoptosis and inhibitory effects on cellular proliferation of taxol through Op18/stathmin in non-small-cell lung cancer cells in vitro." (PMID 32596342, 2020). "A549 and H1299 non-small-cell lung cancer cells and primary cultured heart endothelial cells treated with baicalein have additionally been reported to exhibit downregulated expression of CDK1." (PMID 30891079, 2019). "Considering the report that loss of cytoplasmic Cdk1 expression predicts poor clinical outcome in non-small cell lung cancer patients, we scored Cdk1 expression separately in the nucleus and cytoplasm." (PMID 25511643, 2014). "Non-small cell lung cancer patients with high Cdk1 expression levels also had poorer overall and recurrence survival than those with lower Cdk1 expression." (PMID 25511643, 2014). "Cyclin B1 (in the same family as CDK1) overexpression and/or mislocalisation has been described in several primary cancers, including thyroid carcinoma and colon, gastric, prostate, breast, and non small-cell lung cancers." (PMID 32093341, 2020). "Knockdown of CDK1 was found to defect cell migration in non-small cell lung cancer." (PMID 29903985, 2018). "This might reflect the poor prognosis of non-small cell lung cancer patients with tumors that lost cytoplasm Cdk1 expression." (PMID 25511643, 2014). "However, whether CDK1 directly regulates the histone acetyltransferase KAT8 (also known as MOF) in non-small cell lung cancer (NSCLC) remains unclear." (PMID 42193906, 2026). "In Non-small cell lung cancer (NSCLC), it acts as a tumor suppressor, inducing senescence via SMAD3 interaction and repressing cell cycle regulators such as CDK1 and CCNE2." (PMID 41440013, 2025). "According to another study, CDK1 and HSP90AA1 were also found to be common in their analysis, suggesting that CDK1 and HSP90AA1 play an important role in the regulation of non-small cell lung cancer." (PMID 37764733, 2023).
non-small cell lung carcinoma (continued). "In conclusion, our study identified multiple important genes, including CDK1 and HSP90AA1 which showed differential expression in non-small cell lung cancer patients compared to control through DEG analysis and network building." (PMID 35330393, 2022). "We found that two genes, CDK1 and HSP90AA1, were common in the analysis suggesting a significant regulatory role of CDK1 and HSP90AA1 in non-small cell lung cancer." (PMID 35330393, 2022). "Furthermore, circRNA C190 overexpression facilitated the proliferation, and migration of non-small cell lung carcinoma (NSCLC) cell lines by targeting CDK1 and CDK6 via sequestrating miR-142-5p." (PMID 36059609, 2022). "This suggests significant regulatory roles of CDK1 and HSP90AA1 in non-small cell lung cancer." (PMID 35330393, 2022).
osteosarcoma (26 papers, 2008 to 2025). A usually aggressive malignant bone-forming mesenchymal neoplasm, predominantly affecting adolescents and young adults. "To verify that the effects of PHA-793887 were due to its inhibition of CDK1 in osteosarcoma cells, we assessed CDK1 levels using Western blotting and an enzyme-linked immunosorbent assay (ELISA)." (PMID 34156352, 2021). "Since CDK1 was upregulated in osteosarcoma tissues/cells and associated with a poorer prognosis, we downloaded 20 CDK1-related drugs from the ZINC15 database and assessed their ADME and toxicity properties." (PMID 34156352, 2021). "Western blotting and enzyme-linked immunosorbent assays indicated that CDK1 expression in osteosarcoma cells declined with increasing PHA-793887 concentrations." (PMID 34156352, 2021). "We then performed a survival curve analysis to determine whether TOP2A or CDK1 levels were associated with osteosarcoma patients’ prognoses in the Therapeutically Applicable Research to Generate Effective Treatments dataset." (PMID 34156352, 2021). "STIL is associated with osteosarcoma proliferation and invasion, and may be promote the progression of osteosarcoma by regulating the expression of CDK1, CCNB2, CDC20, CCNA2, BUB1 and AURKB." (PMID 33858425, 2021). "After the suppression of CDK1 expression, it can induce cell cycle arrest at the G2/M phase, thereby inhibiting the proliferation of osteosarcoma cells." (PMID 38297292, 2024). "We have designed and fabricated drug-loaded, magnetic-driven hydrogel micro-robots, and applied them to MYC-dependent osteosarcoma cells, thereby implementing a synthetic lethal strategy that targets CDK1." (PMID 38638876, 2024). "To explore the value of combining magnetic-driven hydrogel micro-robots with CDK1 targeting in the treatment of osteosarcoma, we chose Ro-3306 (a CDK1 inhibitor) as the research drug." (PMID 38638876, 2024). "This study is focused on investigating the therapeutic potential of CDK1 inhibitors for the treatment of MYC-dependent osteosarcoma." (PMID 38638876, 2024). "We have confirmed the sensitivity of MYC-dependent osteosarcoma cells to CDK1 inhibition in vitro and have successfully enhanced the chemotherapeutic responsiveness of these cells." (PMID 38638876, 2024). "Our Western blotting and ELISA results demonstrated that CDK1 expression decreased with increasing drug concentrations, implying that the anti-osteosarcoma effects of PHA-793887 were due to its inhibition of CDK1." (PMID 34156352, 2021). "PHA-793887 dose-dependently inhibited CDK1 expression and induced apoptosis in osteosarcoma cells, thus reducing their proliferation and invasion." (PMID 34156352, 2021). "Various computer-aided techniques were used to identify potential CDK1 inhibitors for osteosarcoma patients, and PHA-793887 was predicted to be a safe drug with a high binding affinity for CDK1." (PMID 34156352, 2021). "Survival curve analyses indicated that osteosarcoma patients with lower mRNA levels of cyclin-dependent kinase 1 (CDK1) and topoisomerase II alpha had better prognoses." (PMID 34156352, 2021). "Apart from G0/G1 arrest, piperine arrests osteosarcoma cells at G2/M phase of cell cycle through the downregulation of cyclin B1 and enhanced phosphorylation of cyclin-dependent kinase-1 (CDK1) and checkpoint kinase 2 (Chk2)." (PMID 29497610, 2018). "In addition, naringenin induced cell cycle arrest in osteosarcoma cells by inhibiting cyclin B1 and cyclin-dependent kinase 1 expression and upregulating p21 expression." (PMID 35056691, 2022). "Melatonin can inhibit human osteosarcoma cell proliferation through downregulation of CDK1." (PMID 33920315, 2021). "Among them, hsa-miR-543, as well as ZNRD1, GPR68, CAT, FUT3, ANPEP, and CDK1 genes, were proposed as crucial players in osteosarcoma chemoresistance, and hence they could represent potential therapeutic targets for osteosarcoma." (PMID 35011442, 2021).
osteosarcoma (continued). "Thus, the upregulation of CDK1 in osteosarcoma patients suggests that it is an important inducer of osteosarcoma and a potential treatment target." (PMID 34156352, 2021). "Likewise, osteosarcoma patients with lower CDK1 levels exhibited significantly longer OS and PFS than those with higher CDK1 levels (P < 0.01)." (PMID 34156352, 2021). "Thus, PHA-793887 dose-dependently reduced the proliferation and invasion of osteosarcoma cells by inhibiting CDK1 and inducing apoptosis." (PMID 34156352, 2021). "Finally, we used molecular docking methods to identify a small molecule inhibitor of CDK1, and conducted cytological experiments to determine its potential as an anti-osteosarcoma drug." (PMID 34156352, 2021). "After identifying CDK1 as a potential therapeutic target in osteosarcoma, we performed a virtual screening, which demonstrated that the small molecular compound PHA-793887 could effectively inhibit CDK1 activity." (PMID 34156352, 2021). "Reduction of CDK1 activities is crucial for the survival of osteosarcoma cells." (PMID 32665038, 2020). "Whether EEF1D directly or indirectly affects CyclinD1/Cdk4 or Cyclin B1/Cdk1 activity in osteosarcomas remains to be investigated." (PMID 29510727, 2018). "And many of them, such as ZNRD1, GPR68, CAT, FUT3, ANPEP, CDK1, and hsa-miR-543, might be key genes related to osteosarcoma chemoresistance." (PMID 29850522, 2018). "As reported, the inhibition of cyclin B and CDK1 led to the arrest of osteosarcoma cell division." (PMID 26337976, 2015). "Thus endoreduplication was seen in human fibrosarcoma cells (HT2-19) with repressible Cdk1 gene expression and in human osteosarcoma (U2OS) cells depleted of Cdk1 by RNA interference." (PMID 18211690, 2008). "Our ongoing research aims to verify whether this synthetic lethal drug-loaded magnetic-driven hydrogel micro-robot can inhibit the in vivo growth of osteosarcoma under the guidance of genomic features and the specific mechanism of CDK1 inhibition in sensitizing osteosarcoma chemotherapy." (PMID 38638876, 2024). "Therefore, combining magnetic-driven hydrogel micro-robots with CDK1 inhibition may be an effective method to improve the chemotherapy sensitivity of MYC-dependent osteosarcoma, and is expected to improve the prognosis of MYC-driven osteosarcoma patients." (PMID 38638876, 2024). "Moreover, the bioinformatics analysis showed that STIL may participate in the biological function of osteosarcoma by regulating CDK1, CCNB2, CDC20, CCNA2, BUB1, and AURKB." (PMID 33858425, 2021). "By suppressing the activities of JUN, HSP90AA1, HDAC1, and CDK1, TGT can impede the growth of osteosarcoma cells." (PMID 38297292, 2024). "Consistent with the network pharmacology results, the RT-PCR experiments showed significant downregulation of JUN, HSP90AA1, HDAC1, and CDK1 expression by TGT, highlighting their potential significance as targets in the anti-osteosarcoma mechanism of TGT." (PMID 38297292, 2024). "In a study on osteosarcoma, it was pointed out that RFC3, CDK1, MAD2L1, NDC80, BUB1, etc. jointly participated in the related links of the disease prognosis of osteosarcoma." (PMID 35483337, 2022). "Another most interesting observation in our study is that a few of the hub genes of Rb tumors including CDK1, CDK2, CCNB1, HDAC1 and UNC5D are reported to play a key role in the pathogenesis of osteosarcoma, the most common secondary cancer in Rb patients." (PMID 35359459, 2022). "Using the 13 gene chips, we found that six hub differentially co-expressed genes (CDK1, CCNB2, CDC20, CCNA2, BUB1, and AURKB) were highly expressed in osteosarcoma." (PMID 33858425, 2021). "Subsequently, we performed qRT-PCR to measure TOP2A, CDK1, MAD2L1, AURKA and RRM2 expression in human normal osteoblast cells (hFOB 1.19) and osteosarcoma cells (MG63, U208 and 143B)." (PMID 34156352, 2021).
osteosarcoma (continued). "We then performed qRT-PCR to assess the expression of five hub genes (TOP2A, CDK1, MAD2L1, AURKA and RRM2) in human normal osteoblast cells and osteosarcoma cells." (PMID 34156352, 2021). "In the PPI network, we selected six genes (CDK1, CCNB2, CDC20, CCNA2, BUB1, and AURKB) as the core STIL differentially co-expressed genes in osteosarcoma." (PMID 33858425, 2021). "Several drugs were reported to inhibit cell proliferation or induce cell cycle arrest and apoptosis in human osteosarcoma by downregulating CCNB1 and CDK1." (PMID 32665038, 2020). "In another investigation with osteosarcoma cells, the induction of a G2/M phase arrest by SFN correlated with a Cdk1 increase." (PMID 33218199, 2020). "KIAA1429 may contribute to the progression of osteosarcoma by targeting CDK1, CCNA2, and CCNB2, which make it possible to become a potential biomarker and therapeutic target of osteosarcoma." (PMID 38164289, 2024). "Consistent with the mouse 45Ca osteosarcoma cell lines, cilia frequency and expression of CDK1, CCNE1 and CDC6 did not correlate with CDKN2A deletion." (PMID 37845394, 2023). "Inactivation of CDK1 and CDK2 triggered the apoptosis of osteosarcoma cells." (PMID 26337976, 2015). "Thus, CDK1 and TOP2A expression could be used to predict the prognosis of osteosarcoma patients." (PMID 34156352, 2021).
lymphoma (22 papers, 2014 to 2025). A malignant (clonal) proliferation of B- lymphocytes or T- lymphocytes which involves the lymph nodes, bone marrow and/or extranodal sites. "A high RIS score was also reported for the positive regulation of the reactive oxygen species (ROS) metabolic process pathway (GO:2000379) associated with the DB cell line (lymphoma) when administered with Dinaciclib (an inhibitor of CDK1, CDK2, CDK5, and CDK9)." (PMID 37432499, 2023). "We thus established that in both the assessed lymphoma cell lines, the expression levels of CDK1, CDK4, and Cyclin B1 were reduced following treatment with artesunate." (PMID 37719860, 2023). "In this study, we clarified the mechanisms through which dinaciclib induces Raji cell apoptosis and blocks the cell cycle through a CDK1‐involved pathway, which supported that dinaciclib had potential values in the treatment of lymphoma." (PMID 31207099, 2019). "The cell apoptosis assay and TUNEL staining showed that the apoptosis rate was dramatically increased in Raji cells with low CDK1 expression, whereas a high CDK1 expression had an inhibitory effect on lymphoma Raji cells (P < 0.05)." (PMID 31207099, 2019). "Furthermore, treating MYC-dependent mouse lymphoma and hepatoblastoma with CDK1 inhibitors has been shown to reduce tumor growth and prolong survival time." (PMID 38638876, 2024). "Our study suggests that the absence of 4E-BP1S82 phosphorylation by CDK1, effected by a single amino acid substitution from S82 to alanine, can predispose to polycystic proliferative disease and lymphoma." (PMID 37145994, 2023). "Additionally, the CDK1 pathway, which was involved in regulating the cell cycle and apoptosis in the lymphoma Raji cell line, was also investigated for its possible regulatory mechanism." (PMID 31207099, 2019). "The treatment with Cdk1 inhibitors is consistently effective also in MYC-dependent mouse lymphoma and hepatoblastoma tumors, suggesting that RSV may be a potential new drug targeting MYC oncogenic pathway." (PMID 28555002, 2017). "Previous studies have shown that CNF2024 induced G2 cell cycle arrest in Hodgkin’s lymphoma cells and decreased cell cycle-related proteins, including CDK1, CDK2, and cyclin D3, along with either G1 or G2 cell cycle arrest in multiple lymphoma cell lines." (PMID 38794139, 2024). "Similarly, the suppression of BUB3, CCNB1, CDCA8, and CDK1 supported mitotic disruption and proliferative collapse in the HKB-11 lymphoma cells upon treatment with the N and UB combination." (PMID 40725093, 2025).
pancreatic ductal adenocarcinoma (20 papers, 2016 to 2025). An infiltrating adenocarcinoma that arises from the epithelial cells of the pancreas. "We also assessed the KRAS/CDK1 SL in cell models of pancreatic ductal adenocarcinoma (PDAC), a disease where where somatic KRAS mutations are prevalent in approximately 90% of cases." (PMID 26881434, 2016). "Additionally, a high expression of CDK1 predicts a poor prognosis of pancreatic ductal adenocarcinoma." (PMID 36568241, 2022). "The cell cycle-related proteins CDK1 and BUB1 are significantly overexpressed in pancreatic ductal adenocarcinoma tissues and may be prognostic biomarkers." (PMID 35515103, 2022).